DDX55 (DEAD-box helicase 55)
Description:
Probable ATP-binding RNA helicase. Has ATPase activity and is involved in the maturation of precursor large subunit rRNAs.
Synonyms: KIAA1595
Tractability: PROTAC: ubiquitination databases record sites on it; its protein half-life has been measured.
Gene: Protein-coding gene on chromosome 12 (123,602,077 to 123,620,943, forward strand). Ensembl gene ENSG00000111364.
Subcellular location: Nucleus, nucleoplasm
Subcellular location (Human Protein Atlas): Nucleoli; Cytosol; Nucleoplasm
Gene Ontology:
Molecular function: ATP hydrolysis activity; large ribosomal subunit rRNA binding; protein binding; RNA binding; ATP binding; nucleic acid binding; RNA helicase activity
Biological process: maturation of LSU-rRNA
Cellular component: cytosol; membrane; nucleolus; nucleoplasm
Genetic constraint (gnomAD): Loss-of-function variants: 56 observed, 69.3 expected, observed/expected ratio (o/e) 0.81, 90% interval 0.65 to 1.01. The upper end of that interval is the gene's LOEUF score, 1.01, which puts it in group 4 of 6, group 1 being the genes least tolerant of losing a copy. Missense variants: 720 observed, 766.18 expected, observed/expected ratio (o/e) 0.94, 90% interval 0.88 to 1. Synonymous variants: 268 observed, 280.15 expected, observed/expected ratio (o/e) 0.96, 90% interval 0.87 to 1.06.
Homologues: Orthologues: chimpanzee DDX55 (99% identical), macaque DDX55 (94% identical), pig DDX55 (94% identical), rabbit DDX55 (91% identical), mouse Ddx55 (91% identical), dog DDX55 (91% identical), rat Ddx55 (91% identical), guinea pig DDX55 (90% identical), zebrafish ddx55 (74% identical), tropical clawed frog ddx55 (68% identical), Drosophila melanogaster CG9630 (48% identical), Caenorhabditis elegans ZK512.2 (36% identical). Paralogues in human: DDX27 (28% identical), DDX10 (28% identical), DDX18 (26% identical), DDX54 (24% identical), DDX31 (24% identical), DDX47 (23% identical), DDX3X (22% identical), DDX24 (22% identical), DDX3Y (22% identical), DDX42 (22% identical), DDX46 (21% identical), DDX17 (21% identical), and 26 more.
Diseases named in the same sentence as DDX55 in open-access papers:
DDX55 is named in the same sentence as 7 diseases in open-access papers, as found by Europe PMC text mining. Sharing a sentence is not in itself a finding about the gene and the disease. The quoted sentences say what the papers report.
hepatocellular carcinoma (2 papers, 2025). A malignant tumor that arises from hepatocytes. "One indication of additional activity of DDX55 was from a recent study that implicated direct interaction between DDX55 and BRD4 as upregulating β-catenin signaling in hepatocellular carcinoma." (PMID 40654921, 2025).
COVID-19 (1 paper, 2023). A disease caused by infection with severe acute respiratory syndrome coronavirus 2. "Our results showed that low levels of DDX55, ANXA1, PICAL, and AGRG6 before treatment, as well as elevated levels of CTRB1 pre-MSC treatment, were biomarkers for predicting response to MSC therapy in severe COVID-19 patients." (PMID 38072927, 2023).
cancer (7 papers, 2012 to 2024). A tumor composed of atypical neoplastic, often pleomorphic cells that invade other tissues. "Abnormally high expression of DDX55 can be used as a reference indicator for poor prognosis of a variety of cancers." (PMID 35847896, 2022). "From the gene-interaction network analysis, we found that the genes with survival-associated AS events including HNRNPA1, RPS5, DDX55, and OFD1 were hub nodes of the network which might play vital roles in cancer progress." (PMID 32595697, 2020). "METTL7A has protein interactions with cancer-related genes BCAS1 and GLIPR1L2, as well as post-transcriptional regulatory genes METTL8 and DDX55." (PMID 37547717, 2023). "In addition, various molecules, including DEAD-box helicase 55 (DDX55), CPE, miR-3129, LINC00161, clathrin light chain A (CTLA), and miR-25, were found to be enriched in cancer-derived exosomes and induce cell proliferation." (PMID 38476233, 2024). "Finally, the Bayesian model also revealed other recurrent genes, FAM60A (family with sequence similarity 60, member A), CMTM7 (CKLF-like MARVEL transmembrane domain 7) and DDX55 (DEAD (Asp-Glu-Ala-Asp) box polypeptide), currently not reported to be involved in cancer progression." (PMID 22280244, 2012).
neoplasia (2 papers, 2012 to 2025). "DEAD-box helicase 55 (DDX55) is enriched in HCC-derived sEVs and promotes tumor invasion and angiogenesis through intercellular transfer." (PMID 40703510, 2025). "FAM60A is also implicated in the tumorigenesis process through protein-DNA interaction with E2F1 (E2F transcription factor 1) and finally, DDX55 expression is indirectly controlled by SOD2(superoxide dismutase 2, mitochondrial), which is directly involved in neoplasia and carcinogenesis." (PMID 22280244, 2012).
DDX55 also shares sentences with these, for which no sentence is quoted: metabolic disease (1 paper); periodontitis (1); urological disease (1).